PHF6 (PHD finger protein 6)
Diseases named in the same sentence as PHF6 in open-access papers (continued):
Sharing a sentence is not in itself a finding about the gene and the disease.
myeloid leukemia (5 papers, 2022 to 2025). A clonal proliferation of myeloid cells and their precursors in the bone marrow, peripheral blood, and spleen. "PHF6 is a chromatin-binding protein mutated in myeloid leukemias, and its isolated loss increases mouse HSC self-renewal without malignant transformation." (PMID 39004675, 2024). "We demonstrated that PHF6 is required for myeloid leukemia cell survival and LSC self-renewal via NF-κB signaling pathway." (PMID 37393343, 2023). "To investigate the mechanisms by which PHF6 regulated NF-κB activity, we assessed the expression of NF-κB related factors in PHF6 KD by shRNA1 myeloid leukemia cells and control cells by Western blotting analysis." (PMID 37393343, 2023). "We did not observe any difference in the nuclear translocation of p65 in PHF6 KD myeloid leukemia cells and control cells after TNFα treatment." (PMID 37393343, 2023). "Taken together, in contrast to PHF6 as a tumor suppressor in T-ALL as reported, we found that PHF6 also plays a pro-oncogenic role in myeloid leukemia, and thus potentially to be a therapeutic target for treating myeloid leukemia patients." (PMID 37393343, 2023). "Since the nuclear translocation of p50 and p65 directly regulates NF-κB downstream target genes, we further assessed the nuclear translocation of p50 and p65 in PHF6 KD myeloid leukemia cells in response to TNFα treatment by immunofluorescence." (PMID 37393343, 2023). "Treating PHF6 over-expressed myeloid leukemia cells with NF-κB inhibitor (BAY11-7082) significantly increased their apoptosis and decreased their proliferation." (PMID 37393343, 2023). "Here with in vivo and in vitro models, we demonstrate that the Plant homeodomain finger gene 6 (PHF6) plays an important role in apoptosis and proliferation in myeloid leukemia." (PMID 37393343, 2023). "It suggested that high PHF6 expression could play a general supporting role in all subtypes of myeloid leukemia." (PMID 37393343, 2023). "Here in this study, we showed that PHF6 played a pro-oncogenic role in myeloid leukemia development induced by RUNX1-ETO9a and MLL-AF9 in mice, while PHF6 is not essential for normal hematopoiesis, suggesting it might be an attractive drug target." (PMID 37393343, 2023). "To further confirm whether PHF6 was truly functional relevant to myeloid leukemia development, we firstly over-expressed PHF6 in Kasumi-1 and K562 cells." (PMID 37393343, 2023). "In addition, PHF6 over-expressing myeloid leukemia cells were more sensitive to NF-κB inhibitor (BAY11-7082) than the other cells, indicating that NF-κB signaling pathways might be a new suppressive target for treatment of myeloid leukemia patients with PHF6 high expression." (PMID 37393343, 2023). "In consistent with their findings, we found that high level of PHF6 predicted an unfavorable prognosis for AML patients, and promoted the growth of myeloid leukemia cells." (PMID 37393343, 2023). "To determine whether inhibition of NF-κB could delay the over-proliferation of PHF6 OE AML cells, we treated PHF6 OE myeloid leukemia cells with BAY11-7082 (a selective NF-κB inhibitor)." (PMID 37393343, 2023). "Notably, the overall amount of p50 was similar in PHF6 KD myeloid leukemia cells and control cells in the presence or absence of TNFα, while the nuclear p50 and p65 significantly decreased after TNFα treatment in PHF6 KD Kasumi-1 and K562 cells when compared with the control cells respectively." (PMID 37393343, 2023).
Tauopathies (5 papers, 2015 to 2025). "It is known that in vivo PHF6* within R2 is present in AD patients only in 50% of neuronal Tau (3R vs. 4R Tauopathies, see)." (PMID 35596819, 2023). "Again, the change of both tau species correlated strongly with the change of PHF6 tau during the development of tauopathy (R2 = 0.70, p < 0.0001 for nY29 and R2 = 0.94, p < 0.0001 for ub-tau)." (PMID 25881209, 2015). "In tauopathies, the transition of tau from a physiological to a pathological form remains unclear, though the hexapeptides PHF6 and PHF6∗ are key in triggering aggregation." (PMID 40264794, 2025). "Interestingly, acetylated tau also showed a strong correlation with PHF6 tau in the insoluble fraction (R2 = 0.76, p < 0.0001), suggesting that both modifications are present in the same pool of tau that contribute to tauopathy and neurodegeneration in this model." (PMID 25881209, 2015).
breast carcinoma (4 papers, 2021 to 2025). "Taken together, these data implicated that PHF6 depends on HIF signaling to potentiate breast cancer progression in vitro and in vivo." (PMID 36967443, 2023). "Taken together, these results implicated that PHF6 could modulate a list of HIF target genes under hypoxia in breast cancer." (PMID 36967443, 2023). "In breast cancer, PHF6 recruits the chromatin-remodeling factor BPTF for epigenetic modifications, thereby enhancing the transcriptional activity of the HIF pathway, which in turn promotes tumor angiogenesis and metabolic reprogramming." (PMID 41515604, 2025). "High expressions of PHF6 in breast cancer are governed by upstream YAP signals and correlate with a poor prognosis for patients." (PMID 38813086, 2024). "PHF6, initially identified as a tumor suppressor, acts as a prognostic epigenetic regulator in breast cancer." (PMID 38813086, 2024). "By analyzing The Cancer Genome Atlas breast cancer (TCGA-Bca) cohort, we found that PHF6 was significantly higher in tumor versus normal tissues." (PMID 36967443, 2023). "The Gene Ontology (GO) bioinformatic results indicated that hypoxia signaling was significantly enhanced in breast cancer patients with upregulated PHF6 expression." (PMID 36967443, 2023). "Considering that PHF6 is a required regulator that drives HIF signaling in breast cancer progression, we thus want to further evaluate its prognostic significance in breast cancer." (PMID 36967443, 2023). "Meanwhile, we observed that breast cancer tissues had notably higher mRNA levels of PHF6 in the ZSH-Bca cohort via qPCR assay (= 35, P < 0.001)." (PMID 36967443, 2023). "Collectively, these findings suggested that PHF6 coordinates HIF1α/HIF-2α to bind to HIF downstream targets in breast cancer cells." (PMID 36967443, 2023). "The Co-IP assay demonstrated the physical interactions between endogenous HIF1α/2α and PHF6 in hypoxic breast cancer cells." (PMID 36967443, 2023). "Collectively, we identified that the epigenetic regulator PHF6 is required for the tumorigenesis of breast cancer." (PMID 36967443, 2023). "To further investigate how PHF6 regulates breast cancer progression, we performed the correlation analysis and identified the top 500 genes with the highest PHF6 correlation coefficient based on the transcriptome data of TCGA-Bca cohort." (PMID 36967443, 2023). "Given the tight associations between PHF6 and hypoxia signaling, we speculated whether PHF6 physically interacts with HIF-1 and HIF-2 in human breast cancer cells." (PMID 36967443, 2023). "The dual luciferase reporter assay further revealed that YAP overexpression could significantly increase PHF6 promoter activity in breast cancer cells, which was even higher induced by YAP-S127A." (PMID 36967443, 2023). "Targeting PHF6/BPTF is effective in breast cancer mouse models." (PMID 36967443, 2023). "To investigate whether HIF is required for PHF6-mediated breast tumor progression, we thus established parental and HIF1α/HIF-2α DKO breast cancer cells overexpressing FLAG-PHF6 or EV." (PMID 36967443, 2023). "In addition, targeting PHF6/BPTF creates an epigenetic vulnerability for breast cancer treatment." (PMID 36967443, 2023). "In contrast, while PHF6 exhibits anti-tumor effects in T-ALL and AML, its overexpression in breast cancer and other cancers promotes the proliferation of cancer cells, exhibiting a tumor-promoting role." (PMID 41515604, 2025). "Under hypoxia, PHF6 interacts with HIF1α/HIF-2α to promote their recruitment to the HRE, thereby driving breast cancer progression." (PMID 36967443, 2023). "Given that PHF6 recruits BPTF to sustain HIF transcriptional activity, we thus wondered whether targeting BPTF using specific inhibitor (AU1) could suppress breast cancer progression." (PMID 36967443, 2023). "Collectively, these data suggested that hypoxia could rely on YAP activation, but not HIF, to sustain PHF6 expressions in breast cancer cells." (PMID 36967443, 2023).
acute leukemia (3 papers, 2021 to 2022). A clonal (malignant) hematopoietic disorder with an acute onset, affecting the bone marrow and the peripheral blood. "An analysis of 29 mixed phenotype acute leukemia cases at Memorial Sloan Kettering Cancer Center revealed PHF6 (23%) and DNMT3A (23%) as the most common recurrent mutations." (PMID 34381727, 2021). "Moreover, PHF6 appears to play a role in lineage plasticity within hematopoietic malignancies, with PHF6 mutations commonly present in mixed phenotype acute leukemias with a predilection for T-lineage marker expression." (PMID 34381727, 2021).
Alzheimer disease (3 papers, 2020 to 2026). A progressive, neurodegenerative disease characterized by loss of function and death of nerve cells in several areas of the brain leading to loss of cognitive function such as memory and language. "On the other hand, Ser285 and Ser289 near the C-terminus of the PHF6* and PHF6 sequences are known to be phosphorylation hotspots for casein kinase 1 (CK1), casein kinase 2 (CK2), and glycogen synthase kinase-3 (GSK-3) in the brains of Alzheimer’s disease patients." (PMID 36003083, 2022).
Coffin-Siris syndrome (3 papers, 2015 to 2020). Coffin-Siris syndrome (CSS) is a rare congenital multi-systemic genetic disorder characterized by aplasia or hypoplasia of the distal phalanx or nail of the fifth digit, developmental delay, intellectual disability, coarse facial features, and other variable clinical manifestations. "The nonsense variant in PHF6 is located in the ePHD2 domain in which causative de novo truncating and missense variants for Börjeson-Forssman-Lehmann syndrome (BFLS) [MIM:301900], and Coffin-Siris syndrome (CSS) [MIM:135900] are known." (PMID 28539120, 2017). "Female patients with de novo PHF6 mutations are nearly indistinguishable from Coffin–Siris syndrome patients during early infancy, but develop a more distinct phenotype as they age, such as the display of linear skin hyperpigmentation, which does not occur in Coffin–Siris syndrome patients." (PMID 26103525, 2015).
endometrial carcinoma (3 papers, 2023 to 2025). A malignant tumor arising from the epithelium that lines the cavity of the uterine body. "We found that the percentage of IFN‐γ+ and TNF‐α+ cells was increased in T cells when cocultured with PHF6 KD or control endometrial carcinoma cells, compared with T cells alone." (PMID 36756714, 2023). "While knockdown of PHF6 in endometrial carcinoma cells increased T‐cell migration by promoting IL32 production and secretion." (PMID 36756714, 2023). "We observed the increased migration of T cells when cocultured with PHF6 KD endometrial carcinoma cells compared with control cells in the lower chambers." (PMID 36756714, 2023). "To determine the effect of PHF6 KD in endometrial carcinoma cells in vivo, we implanted PHF6 KD HEC‐1‐A cells subcutaneously into the immunodeficient NOD SCID gamma mice (NSG)." (PMID 36756714, 2023). "In the T‐cell migration assay, we found that the PHF6 KD endometrial carcinoma cells could promote the infiltration of T cells, which further indicated that PHF6 played an essential role in tumour immune microenvironment in UCEC patients." (PMID 36756714, 2023). "Depletion of PHF6 effectively inhibited the proliferation of endometrial carcinoma cells, which suggested that PHF6 might be a candidate therapeutic target for UCEC patients." (PMID 36756714, 2023). "Knockdown of PHF6 in endometrial carcinoma cells promoted the migration of T cells in UCECs." (PMID 36756714, 2023). "It suggested that PHF6 KD‐1‐induced apoptosis in HEC‐1‐A was not the key cause of the lower growth of endometrial carcinoma cells." (PMID 36756714, 2023). "However, the IFN‐γ and TNF‐α expression was similar in T cells cocultured with PHF6 KD and T cells cocultured with control endometrial carcinoma cells." (PMID 36756714, 2023). "Depletion of PHF6 might delay the growth of endometrial carcinoma cells through decreasing CDK4 expression." (PMID 36756714, 2023). "It is tempting to speculate that blocking PHF6 may enhance the immunotherapy response in endometrial cancers." (PMID 36756714, 2023). "In growth curve assay, knockdown of PHF6 led to a decrease in cell proliferation in HEC‐1‐A and KLE endometrial carcinoma cells." (PMID 36756714, 2023). "Consistent with previous studies, we found that depletion of PHF6 significantly decreased CDK4 expression and inhibited endometrial carcinoma cell proliferation in vitro and in vivo." (PMID 36756714, 2023). "We found that PHF6 KD significantly increased the mRNA expression of IL12 and IL32 in endometrial carcinoma cells." (PMID 36756714, 2023). "In current study, we found that PHF6 affected the CDK4 and IL32 expression through transcriptional regulation in endometrial carcinoma cells." (PMID 36756714, 2023). "Additionally, PHF6 knockout enhanced T cell migration by increasing IL32 production and secretion in endometrial cancer cells." (PMID 41515604, 2025). "To investigate whether PHF6 KD endometrial carcinoma cells could influence the activity of T cells, we analysed the IFN‐γ and TNF‐α expression in T cells when coculture with PHF6 KD or control endometrial carcinoma cells by flow cytometry." (PMID 36756714, 2023). "Consistent with the role of PHF6 in HeLa cells, we found that knockdown of PHF6 significantly reduced the growth of endometrial carcinoma cells by blocking cell cycle, while PHF6 KD did not influence the invasion ability of endometrial carcinoma cells (data not shown)." (PMID 36756714, 2023).
glioma (3 papers, 2019 to 2025). A benign or malignant brain and spinal cord tumor that arises from glial cells (astrocytes, oligodendrocytes, ependymal cells). "Among them, PHF6 has been found to be upregulated in glioma, especially in TMZ resistant GBM, as a potential TMZ-sensitizing factor in resistant GBM cells." (PMID 31798343, 2019). "Furthermore, proteomic analysis reveals high expression levels of PHF6 in cancerous tissues such as lymphoma, glioma, colorectal, and cervical cancer." (PMID 38790189, 2024). "Specifically, PHF6 was negatively correlated with stromal score, immune score, and ESTIMATE score in glioma, lower-grade glioma (LGG), sarcoma (SARC), and lung squamous cell carcinoma (LUSC)." (PMID 41515604, 2025). "Conversely, PHF6 served as a favorable prognostic factor for both DSS and OS in glioma (GBMLGG), skin cutaneous melanoma (SKCM), and kidney renal clear cell carcinoma (KIRC)." (PMID 41515604, 2025).
hepatocellular carcinoma (3 papers, 2021 to 2024). A malignant tumor that arises from hepatocytes. "Additionally, PHF6 proceeds as an oncogene in hepatocellular carcinoma (HCC), promoting tumor growth and progression." (PMID 38813086, 2024). "Studies have shown that PHF6 may significantly promote proliferation and migration and the epithelial-mesenchymal transition (EMT) in hepatocellular carcinoma (HCC) cells." (PMID 34108447, 2021).
T-cell leukemia (3 papers, 2022 to 2024). A malignant disease of the T-lymphocytes in the bone marrow, thymus, and/or blood. "The coexistence of PHF6 and JAK3 mutations in T-ALL patients was frequently noted, but little is known of the mechanism whereby PHF6 mutations promoted JAK3-driven T-cell leukemia." (PMID 36982575, 2023). "pIpC was injected at 3 weeks post-transplantation to delete Phf6 when CD3+ cells in GFP+ cells were above 70% in JAK3M511I-induced T-cell leukemia." (PMID 34465864, 2022). "Notable examples include NOTCH1, PHF6, and FBXW7, which are well-acknowledged for their role in T-cell leukemia, as well as BRAF, which was exclusively predicted in the hairy-cell group, in accordance with its recognized function as a marker for HCL." (PMID 38769532, 2024).
X-linked intellectual disability syndrome (3 papers, 2015 to 2023). "Börjeson-Forssman-Lehmann syndrome (BFLS) is an X-linked intellectual disability syndrome caused by variants in the PHF6 gene." (PMID 37704779, 2023).
B‐cell acute lymphoblastic leukaemia (2 papers, 2023 to 2025). "In B‐cell acute lymphoblastic leukaemia (B‐ALL) models, knockdown of PHF6 significantly reduced B‐ALL cell proliferation." (PMID 36756714, 2023). "Although no translational clinical applications of either JMJD6 or PHF6 in DLBCL have been established to date, JMJD6 is involved in the maintenance and multilineage differentiation potential of HSCs, while the oncogenic effect of PHF6 is suggested in precursor B-cell lymphoblastic leukemia." (PMID 40282457, 2025).
chronic myelogenous leukemia (2 papers, 2015 to 2021). "Isolated cases of loss-of-function PHF6 mutations in chronic myeloid leukemia (CML) and hepatocellular carcinoma patient tumours have also been reported." (PMID 26103525, 2015). "PHF6 mutations are rarely identified in myeloproliferative neoplasms (MPN) (0.7%), occurring in only 1.6% of chronic myelogenous leukemia." (PMID 34381727, 2021).
diffuse large B-cell lymphoma (2 papers, 2022 to 2025). "PHF6 expression showed a negative correlation with MSI in lymphoid neoplasm diffuse large B-cell lymphoma (DLBC)." (PMID 41515604, 2025).
myeloproliferative neoplasm (2 papers, 2021 to 2022). A clonal hematopoietic stem cell disorder, characterized by proliferation in the bone marrow of one or more of the myeloid (i.e., granulocytic, erythroid, megakaryocytic, and mast cell) lineages. "Relatedly, a review of 22 patients with PHF6 mutations in myeloproliferative neoplasms at three institutions revealed an enrichment in cases with increased fibrosis and/or blast crisis." (PMID 34381727, 2021).
neuroblastoma (2 papers, 2020 to 2024). Neuroblastoma (NB) is the most common solid, extracranial childhood tumor. "Utilizing CRISPR/Cas9 we generated PHF6 KO in neuroblastoma SK-N-BE cells." (PMID 33149206, 2020). "In addition, deregulated genes upon PHF6 KO significantly overlapped with deregulated genes after Kdm5c KO and with deregulated genes after TCF4 dosage alterations in neuroblastoma cells but not in human blood after correction for multiple testing." (PMID 33149206, 2020).
breast invasive carcinoma (1 paper, 2025). "PHF6 was identified as an adverse factor for OS in liver hepatocellular carcinoma (LIHC), pancreatic adenocarcinoma (PAAD), and breast invasive carcinoma (BRCA)." (PMID 41515604, 2025).
breast tumors (1 paper, 2023). "The fundamental mechanisms underlying YAP/PHF6/HIF axis in breast tumors endowed novel epigenegtic targets for Bca treatment." (PMID 36967443, 2023). "HIF-DKO abolished PHF6-mediated breast tumor growth, and PHF6 deficiency in turn impaired HIF transcriptional effects." (PMID 36967443, 2023). "Lastly, PHF6 correlated with HIF target gene expression in human breast tumors, which is an independent prognostic regulator." (PMID 36967443, 2023).
cholangiocarcinoma (1 paper, 2025). A carcinoma that arises from the intrahepatic biliary tree (intrahepatic cholangiocarcinoma) or from the junction, or adjacent to the junction, of the right and left hepatic ducts (hilar cholangiocarcinoma). "Results indicated a positive correlation between PHF6 and DNAss in OV and a negative correlation in cholangiocarcinoma (CHOL) and DLBC." (PMID 41515604, 2025).
developmental delay (1 paper, 2025). "The PHF6 variant (p.T255del), while not present in the public databases, has been reported before in another patient with developmental delay and dysmorphic facial features." (PMID 40869981, 2025).